SOX10 (SRY-box transcription factor 10)
Diseases named in the same sentence as SOX10 in open-access papers (continued):
Sharing a sentence is not in itself a finding about the gene and the disease.
soft tissue neoplasm (5 papers, 2013 to 2025). A benign, intermediate, or malignant neoplasm that arises from the soft tissue. "Similarly, SOX10 staining is characteristic of melanocytic tumors and soft tissue neoplasms with neural crest origin." (PMID 38902365, 2025). "However, similarly to S100, SOX10 exhibits a low specificity, being potentially expressed by a large number of tumors (carcinomas and soft tissue tumors), and it should be always used in conjunction with other immunohistochemical markers, depending on the diagnostic scenarios." (PMID 35682589, 2022).
adenoid cystic carcinoma (4 papers, 2021 to 2024). A malignant tumor arising from the epithelial cells. "Adenoid cystic carcinoma and polymorphous adenocarcinoma have consistently demonstrated SOX10 expression in virtually all cases studied." (PMID 38132479, 2023). "Of note, only 1 of the 5 tumors with positivity for SOX10 and weak reactivity with HMB45 represented invasive breast carcinoma of no special type, with the remainder representing special histologic types (3 adenoid cystic carcinomas and 1 metaplastic carcinoma)." (PMID 37306115, 2024).
alveolar rhabdomyosarcoma (4 papers, 2021 to 2024). A rapidly growing malignant mesenchymal neoplasm. "Just to complicate it further, despite Sox-10 being a good marker for tumors that originate from neural-crest-derived cells, myoepithelial cells and alveolar rhabdomyosarcoma can also have Sox-10 expression." (PMID 36669002, 2022). "Of the non-neural, nonmelanocytic sarcomas, only one rhabdomyosarcoma sample was positive for SOX10." (PMID 38132479, 2023). "Among non-nerve sheath tumors, positive SOX10 tumor cells were identified only in alveolar rhabdomyosarcoma (2/27) and ossifying fibromyxoid tumors (2/47)." (PMID 38132479, 2023).
colorectal cancer (4 papers, 2014 to 2024). A primary or metastatic malignant neoplasm that affects the colon or rectum. "Notably, overexpression of SOX10 suppressed the establishment of colorectal cancer liver metastasis." (PMID 25301735, 2014). "We also found that SOX10 could be activated in the colorectal cancer cell line HCT116 which is completely methylated for this gene, by genetic demethylation through only double knockout (KO) of both DNMT1 and DNMT3B (DKO cell line), but not single KO of DNMT1 or DNMT3B alone (1KO or 3BKO cell line)." (PMID 25301735, 2014). "Given that overexpression of NEDD9 implies poor prognosis in colorectal cancer patients, we confirmed a dramatic effect of MLT (0.5, 1 mM) and/or Ptero (20, 40 μM) on NEDD and SOX10/9, especially in SW480 and HT29 CRCs better than in HCT116 cells." (PMID 31671847, 2019).
demyelinating disease (4 papers, 2014 to 2024). A broad group of disorders that affect the myelin sheaths that cover the neurons. "The discovery of a SOX10 mutation as a perpetrator (and the exclusion of other known mutations such as PMP22) in PCWH, a demyelinating disease, further supported the role of SOX10 in Schwann cell differentiation." (PMID 38132479, 2023).
demyelination (4 papers, 2020 to 2022). "Sox10-GFP expressing viral particles were injected into cuprizone-induced demyelination mice brains." (PMID 36289861, 2022). "The brains of mice from the cuprizone-induced demyelination model were collected at days 42, 49, and 56 to assess the number of SOX10-positive (oligodendrocyte lineage cells) and GST-pi-positive cells (oligodendrocytes) in the corpus callosum." (PMID 34987466, 2021). "This study aimed to analyze changes in Sox10 expression in the hippocampus and its regulatory role in hippocampal myelin regeneration in a mouse model of demyelination." (PMID 32363773, 2020).
gastric cancer (4 papers, 2016 to 2025). A primary or metastatic malignant neoplasm involving the stomach. "SOX10 has also been strongly associated with an increased risk of perineural invasion in gastric cancer." (PMID 40159622, 2025). "Thus, SOX10 can regulate cell proliferation and gastric cancer progression by regulating the expression of CMTM7 (Jin, Qin & Jia, 2018)." (PMID 38223763, 2024). "Consistent with that, our results also indicated that SOX10 was significantly downregulated in gastric cancer, implying that the reduction of SOX10 expression could be a good predictor for gastric cancer." (PMID 27403158, 2016). "SOX10 overexpression in cell lines with silenced CMTM7 expression can significantly inhibit cell proliferation and gastric cancer progression." (PMID 38223763, 2024). "SOX10, a transcriptional regulator of CMTM7, mediates CMTM7 expression in gastric cancer." (PMID 38223763, 2024).
myoepithelial carcinoma (4 papers, 2021 to 2025). "Immunostaining showed that this tumor was negative for S100, SOX10, smooth muscle actin, and p63, arguing against myoepithelial carcinoma." (PMID 40366517, 2025). "Our cases were entirely negative for S100 and SOX10, which, in combination with SMARCB1, negativity excludes myoepithelial carcinoma." (PMID 38085333, 2024).
PCWH syndrome (4 papers, 2021 to 2025). "For the child with PCWH syndrome, both the small and large intestine showed a reduction in the number of glial cells (SOX10), in parallel with hypoganglionosis (HuC/D), when compared with “age‐matched” controls." (PMID 40364458, 2025). "Here, we report the histological findings observed in two newborn children: one with clinically defined PCWH syndrome (SOX10; c.769A>T, p.Lys257*) and one with clinically defined WSS (EDN3; c.472C<T, p.Arg158Cys)." (PMID 40364458, 2025).
perineurioma (4 papers, 2022 to 2025). A usually benign perineurioma not associated with a nerve, arising from the soft tissues. "Four MNSTs (6.0%) were strongly immunoreactive for claudin-1 and negative for Sox10 and GFAP and were accordingly classified as MNSTs with perineurial differentiation or malignant perineurioma." (PMID 35622732, 2022).
smooth muscle tumor (4 papers, 2022 to 2025). A benign or malignant myomatous neoplasm arising from smooth muscle. "Moreover, in tumors with the following immunoprofile: S100+, SOX10-, SMA+ (diffuse reactivity) and the possibility of SMT should be taken into consideration and the confirmation of this diagnosis by expression of smooth muscle tumor markers is required." (PMID 36292216, 2022).
spindle cell tumor (4 papers, 2013 to 2025). "This study shows that most facial spindle cell tumors were compatible with peripheral nerve sheath tumors (PNSTs) based on positive immunohistochemical staining for Sox10 and other immunohistochemical markers such as GFAP, NSE, and S100." (PMID 38612342, 2024). "Histology of the peripheral parts of the lesion demonstrated a cellular spindle cell tumor with central degeneration, positive for SOX10, S100 and GFAP." (PMID 37535242, 2023).
uterine sarcomas (4 papers, 2023 to 2025). "S100/SOX10-positive uterine sarcoma with ERBB2/ERBB3 mutation is a newly recognized and highly aggressive subtype of uterine sarcoma characterized by aberrant HER2 pathway activation and neural crest-like immunophenotype." (PMID 41463261, 2025). "In summary, we herein describe the first detailed study of a novel ERBB2/ ERBB3-mutated S100/SOX10-positive unclassified highly aggressive uterine sarcoma type." (PMID 39196362, 2024). "SOX10 lacks expression in a category of uterine sarcomas with NTRK fusions, distinguishing them from undifferentiated uterine sarcomas and aggressive leiomyosarcomas." (PMID 38132479, 2023). "Inclusion of SOX10 in high-grade unclassified gynecological sarcomas would be a valuable and cheap screening tool to enhance recognition of this entity, particularly in putative cases of undifferentiated uterine sarcomas." (PMID 39196362, 2024). "However, the inclusion of SOX10 as a screening tool in high-grade unclassified uterine sarcomas could enhance recognition of this entity, especially in putative cases of undifferentiated uterine sarcomas, and could enhance the precision of the diagnosis and treatment strategies." (PMID 40001568, 2025).
viral infection (4 papers, 2021 to 2024). "The loss of SOX10 promotes a cross-resistant state by further inhibiting viral infection and replication." (PMID 38201278, 2023). "Therefore, we hypothesized that the loss of SOX10 in MAPKi-resistant cells could induce resistance to oncolytic virus infection." (PMID 38201278, 2023). "Through analyses of the stage alteration rate of reporter-containing cells from day 1 to day 2 after viral infection, we can conclude that the Sox10+/rtTA-targeting cells at day 0 should mostly be OPCs and NFOs." (PMID 34725188, 2021). "We analyzed the densities of TCF4+YFP+ cells and found that they reduced to half from day 1 to day 2 after viral infection in Sox10+/rtTA mice at either P14 or P35." (PMID 34725188, 2021). "Apart from one study conducted in vitro, Sox10+ cells have not been linked with Type I IFN induction during viral infection." (PMID 39159381, 2024). "Of the top 14 enriched biological processes in the SOX10-deficient A375, two were associated with the negative regulation of viral infection." (PMID 38201278, 2023). "Interestingly, SOX10 has been associated with the regulation of immune-related pathways, including IRF1, a well-characterized regulator of viral infection." (PMID 38201278, 2023).
albinism (3 papers, 2017 to 2024). A congenital disorder characterized by partial or complete absence of melanin pigment in the eyes, hair, or skin. "The depigmentation phenotype of the transgenic SOX10 mutation miniature porcine model has been studied for its albinism and its similarity to the WS2 phenotype." (PMID 29922125, 2018).
campomelic dysplasia (3 papers, 2012 to 2021). "Finally, in agreement with our expression studies on human skin, humans carrying mutations in SOX9 display campomelic dysplasia affecting the skeleton and reproductive system but not melanocytes, whereas patients with mutations in SOX10 often exhibit pigmentary anomalies." (PMID 25629959, 2015).
Cerebral ischemia (3 papers, 2020 to 2025). Restriction of arterial blood supply to the brain associated with insufficient oxygenation to support the metabolic requirements of the tissue. "This study aimed to trace Sox10 cells after LPS-induced inflammation and cerebral ischemia in male and female mice." (PMID 39106252, 2024). "Here, although cerebral ischemia did not affect Sox10 expression, EPI‐NCSCs transplantation caused elevated expression of this transcript suggesting formation of different glial cells types." (PMID 32281225, 2020). "The reverse transcription (RT)-qPCR results demonstrated that LIPUS treatment increased the expression levels of pro-differentiation-related genes (Olig2 and Sox10), as well as a significant up-regulation of myelin-related genes such as PLP, MBP, and MOG in mice with cerebral ischemia." (PMID 40290135, 2025). "Our findings indicate that Sox10 cells do not differentiate into pericytes, neurons, astrocytes, or microglia following brain ischemia." (PMID 39106252, 2024).
colon carcinoma (3 papers, 2013 to 2019). "The impact of SOX10 overexpression on β-catenin/TCF activity was further examined in HCT116 colon cancer cells which contain a heterozygous activating mutation in β-catenin." (PMID 25301735, 2014). "In order to validate the implication of SOX9 and/or SOX10 factors in meloe promoter activation, we co-transfected expression vectors coding these factors, together with the P-644 plasmid in a colon carcinoma cell line (SW480) and a mesothelioma cell line (Meso163)." (PMID 24086527, 2013).
developmental delay (3 papers, 2019 to 2024). "SOX10, a risk gene associated with developmental delay, was expressed at the highest level when OPCs differentiated into oligodendrocytes." (PMID 39363111, 2024). "The other associated symptoms observed in SOX10 cases were ptosis (JHLB4270, JHLB4310), developmental delay (JHLB4310) and Asperger syndrome (JHLB3480)." (PMID 31427586, 2019). "We identified one SOX10-assiociated WS case with developmental delay and one with Asperger syndrome." (PMID 31427586, 2019). "Both of these cases carried truncation variants; however, no cases were observed with developmental delay among the SOX10 CNV cases." (PMID 31427586, 2019). "Our case (Pt7) presented with mild developmental delay and diffuse hypomyelination without the involvement of other systems, which may suggest another form of SOX10 related disorder." (PMID 33597727, 2021).
diabetes (3 papers, 2018 to 2026). "The presence of Sox10-HuC/HuD-immunoreactive cells and their diabetes-related quantitative changes were also revealed in enteric plexuses." (PMID 42072342, 2026). "E2f1, Sox10 and SP1 were found to likely regulate the expression of genes found only in diabetes." (PMID 38039846, 2024). "Chloe Stenkamp16 and his colleague reported that obesity and diabetes progressed in high-fat diet mice did not alter S100β, Sox10 and GFAP expression in myenteric of EGC." (PMID 30140011, 2018).
dysplastic nevus (3 papers, 2023 to 2025). Clinically atypical nevi (usually exceeding 5 mm in diameter and having variable pigmentation and ill defined borders) with an increased risk for development of non-familial cutaneous malignant melanoma. "Cases identified as dysplastic nevus, NIM, or IM undergo routine immunohistochemistry, typically using markers such as SOX10 and MelanA." (PMID 39824857, 2025). "Markers, such as Melan-A, HMB-45, SOX-10, and PRAME, assist the dermopathologist on a daily basis in the differential diagnosis between severe dysplastic nevus and MIS." (PMID 36975387, 2023).
leukemia (3 papers, 2016 to 2021). A malignant (clonal) hematologic disorder, involving hematopoietic stem cells and characterized by the presence of primitive or atypical myeloid or lymphoid cells in the bone marrow and the blood. "Moderate enrichment of DNA-binding motifs for embryonic transcription factors (for example, Sox10 and Eomes) and T-cell transcription factors (for example, Tbet and GATA3) were found, consistent with adoption of a more primitive transcription program in MLLr leukemia." (PMID 27462455, 2016).
lung adenocarcinoma (3 papers, 2019 to 2024). A carcinoma that arises from the lung and is characterized by the presence of malignant glandular epithelial cells. "Of the breast markers, SOX10 has been shown to have the highest sensitivity and specificity (compared to GATA3, MGB and GCDFP-15) to discriminate between TNBC and lung adenocarcinomas to reflect the differential diagnosis of TNBC metastatic to the lung." (PMID 37012444, 2023).
lung carcinoma (3 papers, 2018 to 2023). "A previous study demonstrated that EMT is involved in the process of metastatic dissemination to the brain, and the EMT driver genes that were upregulated in our study (SOX10, TWIST1, CDH2) may have potential as biomarkers in risk stratification for BM in suspected early-stage lung cancer." (PMID 37139160, 2023). "The later study included five normal lung samples and 25 neoplastic lung cancer samples, all of which were negative for SOX10." (PMID 30205833, 2018).
metastatic disease (3 papers, 2016 to 2025). "In addition, our study was limited to primary tumor samples and we didn’t assess the diagnostic utility of SOX10 IHC stain in metastatic tumor samples which are more challenging cases in real practice." (PMID 38813332, 2024). "In overall BC, SOX10 demonstrates the most concordant expression between primary and metastatic tumors (96.4%, κ=0.663) when compared with other breast-specific markers." (PMID 38813332, 2024). "SOX10 has emerged as a sensitive IHC marker for TNBC which also shows better concordance between primary and metastatic tumors." (PMID 38813332, 2024). "These 13 SOX10 negative patients, that had so far untreated metastatic disease, may represent an immunosuppressed subgroup, or a subgroup that express no or very low levels of SOX10 in their tumors." (PMID 27110718, 2016).
nasopharyngeal carcinoma (3 papers, 2018 to 2025). A carcinoma arising from the nasopharyngeal epithelium. "In nasopharyngeal carcinoma, loss of SOX10 obviously inhibited cell proliferation, migration, and invasion, as well as the EMT process." (PMID 40458751, 2025). "Marked overexpression of SOX10 is observed in nasopharyngeal carcinomas;Higher expression is associated with a poorer prognosis, and SOX10 is believed to be involved in tumor growth and metastasis;Potential importance as a diagnostic and prognostic marker." (PMID 38132479, 2023). "The overexpression of SOX10 in nasopharyngeal tumors highlights its potential importance as a diagnostic and prognostic marker for patients with nasopharyngeal carcinoma." (PMID 38132479, 2023). "In nasopharyngeal carcinomas, SOX10 is markedly overexpressed, and this overexpression is associated with a poorer prognosis, particularly in T classification and lymph node metastasis." (PMID 38132479, 2023).
oncocytomas (3 papers, 2023 to 2025). "Oncocytic pleomorphic adenoma and myoepithelioma with novel gene fusions in a subset of cases What is hiding behind S100 protein and SOX10 positive oncocytomas?" (PMID 36622399, 2023). "The characteristic immunoprofile of oncocytoma demonstrates consistent positivity for antimitochondrial antigen and epithelial markers, while being negative for S100, SOX10, and SMA." (PMID 40770850, 2025). "Among the 14 benign tumors analyzed significant overexpression of SOX-10 protein was found only in pleomorphic adenomas, with no overexpression observed in Warthin’s tumors or oncocytomas." (PMID 39684268, 2024).
paraganglioma (3 papers, 2024 to 2025). A benign or malignant neoplasm arising from paraganglia located along the sympathetic or parasympathetic nerves. "Formal diagnosis of paragangliomas is confirmed through histopathology, with characteristic sustentacular cells stained positively for S100 and SOX10." (PMID 39839207, 2025). "Our results add to existing data suggesting that, unlike humans, even early embryonic (Sox10‐driven) SDHx loss is inadequate to trigger paraganglioma in mice of the genetic backgrounds that have been investigated." (PMID 39399478, 2024). "Additionally, the maxillary location and the negative staining for S100, SOX10, and GATA3 do not support a diagnosis of paraganglioma or olfactory neuroblastoma." (PMID 39404971, 2024).
solitary fibrous tumor (3 papers, 2022 to 2025). Solitary fibrous tumor (SFT) represents a diverse group of ubiquitous rare spindle cell neoplasms that may be benign or malignant and that most frequently arises from the pleura and peritoneum and rarely from other sites such as head and neck, liver and skeletal muscle. "DFSP typically exhibits strong CD34 positivity, while other markers, such as S100, SOX10, and STAT6, help exclude neural or solitary fibrous tumor variants." (PMID 41431584, 2025).
spindle cell melanoma (3 papers, 2021 to 2025). A melanoma characterized by the presence of malignant spindle-shaped melanocytes. "Immunohistochemistry with melanocytic markers such as Sox10 and S100 protein is often helpful; however, even in cases with pigment deposition in cellular blue nevi, another differential diagnosis must be made, which includes spindle cell melanoma and dermal metastasis of spindle cell melanoma." (PMID 40843873, 2025). "With the negativity of SOX10, Melan A, and HMB45, it does not support desmoplastic/spindle cell melanoma." (PMID 34940081, 2021).
spindle cell sarcoma (3 papers, 2020 to 2024). A malignant mesenchymal neoplasm composed of spindle-shaped cells. "Match of both tumors to the MPNST-like class, together with the retained H3K27me3 in both samples, and the negativity for SOX10 of the primary lesion, led to a final diagnosis of high-grade undifferentiated spindle cell sarcoma." (PMID 38178234, 2024). "According to immunohistochemical findings, the final diagnosis was changed to “high-grade undifferentiated spindle cell sarcoma” for two cases belonging to the same patient, since both displayed positive H3K27me3, and one was also negative for SOX10." (PMID 38178234, 2024).